TMEM18 (transmembrane protein 18)
Description:
Transcription repressor. Sequence-specific ssDNA and dsDNA binding protein, with preference for GCT end CTG repeats. Cell migration modulator which enhances the glioma-specific migration ability of neural stem cells (NSC) and neural precursor cells (NPC).
Synonyms: DKFZp434C1714; lncND
Tractability: Antibody: UniProt predicts a signal peptide or a membrane-spanning region. PROTAC: ubiquitination databases record sites on it.
Gene: Protein-coding gene on chromosome 2 (663,877 to 677,470, reverse strand). Ensembl gene ENSG00000151353.
Subcellular location: Cytoplasm; Nucleus membrane
Subcellular location (Human Protein Atlas): Mitochondria; Endoplasmic reticulum
Gene Ontology:
Biological process: cell migration
Cellular component: cytoplasm; nuclear membrane
Genetic constraint (gnomAD): Loss-of-function variants: 14 observed, 18.26 expected, observed/expected ratio (o/e) 0.77, 90% interval 0.5 to 1.2. The upper end of that interval is the gene's LOEUF score, 1.2, which puts it in group 5 of 6, group 1 being the genes least tolerant of losing a copy. Missense variants: 187 observed, 174.79 expected, observed/expected ratio (o/e) 1.07, 90% interval 0.95 to 1.21. Synonymous variants: 86 observed, 68.81 expected, observed/expected ratio (o/e) 1.25, 90% interval 1.05 to 1.5.
Homologues: Orthologues: macaque TMEM18 (95% identical), chimpanzee TMEM18 (89% identical), dog TMEM18 (84% identical), mouse Tmem18 (78% identical), guinea pig TMEM18 (75% identical), rat Tmem18 (74% identical), pig TMEM18 (74% identical), rabbit TMEM18 (69% identical), tropical clawed frog tmem18 (57% identical), zebrafish tmem18 (54% identical), Drosophila melanogaster Tmem18 (39% identical).
Diseases named in the same sentence as TMEM18 in open-access papers:
TMEM18 is named in the same sentence as 20 diseases in open-access papers, as found by Europe PMC text mining. Sharing a sentence is not in itself a finding about the gene and the disease. The quoted sentences say what the papers report.
Obesity (79 papers, 2010 to 2025). Accumulation of substantial excess body fat. "Interactions between the TMEM18 variant and shift work and inadequate sleep were also significantly associated with higher obesity traits in this study." (PMID 39283705, 2025). "TMEM18 rs939583 was included in another GRS associated with BMI in individuals with extreme obesity compared to lean controls." (PMID 38732542, 2024). "Consuming 1–3 glasses of wine per week was found to have a protective effect against obesity risk for TMEM18 rs939583 ALT allele carriers." (PMID 36678137, 2023). "Our study demonstrated that weekly consumption of 1–3 glasses of wine reduced obesity risk by 35% (OR = 0.65 95% CI 0.52–0.81; p < 0.001) for TMEM18 rs939583 variant homozygotes." (PMID 36678137, 2023). "We showed that both SSBs and flavored water consumption significantly interact with TMEM18 rs939583 to elevate obesity risk." (PMID 36678137, 2023). "Earlier studies have demonstrated the association of common TMEM18 SNPs with a higher obesity risk in childhood, partly due to the down-regulation of TMEM18 expression in adipocytes leading to adipocyte disfunction." (PMID 36678137, 2023). "Carriers of common TMEM18 SNPs linked to obesity can modify their lifestyle behaviors that interact with their genetic predisposition, in particular, measurable PA and moderate wine consumption." (PMID 36678137, 2023). "TMEM18 genetic polymorphisms have been identified as an important risk factor for obesity, depending on ethnic population and age." (PMID 36678137, 2023). "PA significantly attenuated the TMEM18 rs939583 ALT allele homozygotes (TT) obesity risk compared to the inactive ALT allele homozygotes carriers." (PMID 36678137, 2023). "We analyzed TMEM18 rs939583, rs1879523 and surrogate SNPs previously reported to be associated with obesity across five genetic models: allelic, dominant, recessive, additive and codominant." (PMID 36678137, 2023). "Scientific evidence supports an interaction between PA and genetic background on obesity disposition, including evidence on the attenuating effect of PA on TMEM18 obesity predisposition." (PMID 36678137, 2023). "Various polymorphisms in the TMEM18 loci have been implicated in obesity through GWAS and observational studies, an association more pronounced in the pediatric population." (PMID 36986146, 2023). "The TMEM18 gene is an obesity-associated gene involved in the regulation of the hypothalamic pathways that regulate appetite and body weight." (PMID 36678137, 2023). "Common TMEM18 SNPs were significantly linked with adult obesity risk and interacted with modifiable lifestyle factors." (PMID 36678137, 2023). "Clearly, association between obesity and TMEM18 polymorphisms are needed to be confirmed to determine their precise effect in diverse populations." (PMID 36678137, 2023). "Regarding adults, studies on the common TMEM18 SNPs associated with obesity have been inconsistent across different populations, pointing to possible population-related associations." (PMID 36678137, 2023). "TMEM18 rs939583 and rs1879523 were significantly associated with increased obesity risk (OR = 1.35, 95% CI (1.17–1.57) and OR = 1.66, 95% CI (1.29–2.15), respectively)." (PMID 36678137, 2023). "We have shown that common TMEM18 locus SNPs, rs939583 and rs1879523, are significantly associated with an elevated obesity risk in the adult Israeli population." (PMID 36678137, 2023). "Of these, the SNP rs2867112 is near the protein-coding gene body TMEM18, and genetic variants in the proximity of the gene have been linked to obesity, insulin levels, and blood glucose levels." (PMID 35250867, 2022). "Of the identified genes in our study, FTO, GNPDA2, MC4R, MTCH2, NEGR1, SH2B1, TMEM18 are unequivocally regarded as obesity genes associated with PCOS, as supported by contemporary evidence." (PMID 35679284, 2022).
Obesity (continued). "TMEM18 is an important susceptibility locus for obesity, which is an independent risk factor for the development and progression of T2D and CVDs." (PMID 35250867, 2022). "Another study has shown that SEC16B and TMEM18 were associated with 27% and 40% increased odds of obesity, respectively, in Hispanic/Latino children (22–88% frequency)." (PMID 36499740, 2022). "Variants in MC4R, SEC16B and TMEM18 that associated with coffee consumption in previous GWAS are also GWAS-confirmed obesity loci." (PMID 34903748, 2021). "The present meta-analysis was performed to evaluate the association of SNPs near TMEM18 with obesity with regard to age, i.e. children and adults, as well as population type." (PMID 34229657, 2021). "If TMEM18 polymorphisms serve as risk factors for obesity, then it would be reasonable to assume that the alleles: C of rs6548238, T of rs4854344, T of rs11127485, C of rs2867125, G of rs7561317 will occur more often in obese people." (PMID 34229657, 2021). "The present meta-analysis is the first to systematically explore the association between TMEM18 polymorphisms and obesity across different population types based on ethnicity and age." (PMID 34229657, 2021). "The results of this meta-analysis suggest an association between rs6548238 polymorphisms and its surrogate near TMEM18 and the risk of obesity." (PMID 34229657, 2021). "In the case of TMEM18, it has been linked to obesity in multiple studies, which would seem an interesting contrast with the results of this study, as SNPs near this gene were identified in our cohort of non-obese diabetic cats." (PMID 34874954, 2021). "The association between TMEM18 and obesity-related anthropometric parameters is in line with the literature." (PMID 33801339, 2021). "Among them, TMEM18 gene seems to be mostly identified in various studies prevalently dealing with the topic of obesity, including adiposity, in relation to specific polymorphisms." (PMID 32244494, 2020). "The linear regression showed that the rs7561317 polymorphism of TMEM18 is negatively associated with obesity." (PMID 31354816, 2019). "Only both TMEM18 (rs6548238; rs7561317) polymorphisms were found associated with obesity (OR=0.5, P=0.008) and were in linkage disequilibrium (r2=0.87)." (PMID 31354816, 2019). "Though not significant, suggestive AM associations included LPL and CYP4F22, which are associated with type 2 diabetes and lipid metabolism (rs1372339, rs4922116, rs1273516), and TMEM18 (rs2947411), associated with obesity and body mass index." (PMID 23424626, 2013). "Subsequent articles confirmed the role of TMEM18 as an obesity risk in adult Europeans, extended the linkage to childhood and adolescent obesity, and the obesity of Japanese." (PMID 21980424, 2011). "A different pattern was observed for the TMEM18 rs7561317 G-allele, which strongly associated with obesity with an OR of 1.25 (1.14–1.37, p = 2.1×10−6) and with morbid obesity with an OR of 1.46 (1.17–1.82, p = 8.3×10−4) per allele, but not with overweight." (PMID 21912638, 2011). "TMEM18 is a hypothalamic gene that has recently been linked to obesity and BMI in genome wide association studies." (PMID 20380707, 2010). "We also investigated the risk of obesity for variants upstream of the TMEM18 locus in the cohort of severely obese children and healthy controls, and performed the first examination of the locus association to several obesity-related traits." (PMID 20380707, 2010). "There was a strong association for two SNPs (rs6548238 and rs756131) of the TMEM18 locus with an increased risk for obesity (p = 0.001 and p = 0.002)." (PMID 20380707, 2010). "We also re-identified variants in or near FTO, MC4R, and TMEM18 to be associated with extreme obesity." (PMID 20421936, 2010). "However, biases related to genetic predispositions must be considered, as genes such as FTO, MC4R, PPARG, and TMEM18 are associated with obesity and metabolic disorders, especially in European populations." (PMID 40827223, 2025).
Obesity (continued). "Regarding the TMEM18 rs7561317 variant, interactions of the risk allele “G” with random eating patterns, tendency toward fat-dense food, and irregular sleep significantly increased all obesity traits, including BMI, WC, HC, WHR, WHtR, and BF%." (PMID 39283705, 2025). "In addition, there are some other proteins with significant changes, such as TMEM18, which has been associated with obesity in both adults and children." (PMID 39684655, 2024). "Thus, we analyzed common TMEM18 SNPs associated with obesity and actionable lifestyle factors in the Israeli population." (PMID 36678137, 2023). "Common TMEM18 gene SNPs rs939583 and rs1879523 are significantly associated with obesity risk." (PMID 36678137, 2023). "Indeed, our results elucidate the importance of the reduction or elimination of SSBs, including flavored water which contains added sugars, particularly in people with TMEM18 SNPs predisposing obesity." (PMID 36678137, 2023). "However, differences in the TMEM18 locus and obesity risk appear to exist between ethnic populations and age groups." (PMID 36678137, 2023). "The TMEM18 locus has been identified and confirmed by several subsequent genome-wide association studies (GWASs) for single nucleotide polymorphisms (SNPs) associated with obesity and BMI." (PMID 36678137, 2023). "Our findings show that carriers of the TMEM18 rs939583 and rs1879523 SNPs have a significantly elevated obesity risk (OR = 1.21 95% CI 1.06–1.39; p = 0.002) and for the rs939583 C allele, which has a slightly lower risk (OR = 1.32 [1.10–1.59]) found for Europeans descendants." (PMID 36678137, 2023). "Furthermore, TMEM18 locus obesity associated polymorphisms have been scarcely studied in relation to the interaction with modifiable environmental factors." (PMID 36678137, 2023). "This research aimed to study the association of common TMEM18 polymorphisms with obesity and their interactions with modifiable factors, namely drinking habits (sugar-sweetened beverages (SSBs), flavored water and wine) and physical activity (PA) in the Israeli population." (PMID 36678137, 2023). "Therefore, this present meta-analysis examines the relationship between TMEM18 polymorphisms with the risk of obesity with regard to age group and ethnic population." (PMID 34229657, 2021). "The polymorphisms near TMEM18 appear to play a role in the development of obesity." (PMID 34229657, 2021). "In 2009, the Genetic Investigation of Anthropometric Traits Consortium conducted a large-scale meta-analysis involving more than 32,000 European subjects and found that the locus near TMEM18 (rs6548238) was associated with obesity, with allele C being more important than allele T." (PMID 32228543, 2020). "In the case of the promising candidate, SNPs within the NYD-SP18 gene area, the potential physiological link between this gene and obesity remain unknown; however, this applies to some extent to most obesity-associated genes (such as TMEM18 or FTO)." (PMID 27237450, 2016). "Amongst the adiposity-related genetic variants, we chose single nucleotide polymorphisms (SNPs) within the most common major adiposity genes FTO, MC4R and TMEM18, all of which have been recognized to be associated with obesity and explaining a variance of about 1–2%." (PMID 22723994, 2012). "The current study focused on variants located within and around FTO, MC4R and TMEM18 that are amongst the genes most strongly associated with obesity traits and also identified in earlier meta-analyses, despite the fact that the variance explained by these loci is small (1–2%)." (PMID 22723994, 2012). "TMEM18 has been implicated in complex phenomena like cancer, cell migration, and obesity." (PMID 21980424, 2011). "Aside from FTO, GWA studies associated with obesity yet another gene, named TMEM18." (PMID 20380707, 2010).
Obesity (continued). "Triglyceride level was another trait associated with the C allele of TMEM18 rs6548238 that was altered in this study, a phenomenon also observed in the Chinese population; this effect may be related to its ability to induce obesity." (PMID 37761915, 2023). "Therefore, we speculated that the locus near TMEM18 (rs6548238) may increase diabetes risk via inducing obesity and insulin resistance." (PMID 32228543, 2020). "The objective of the present study was to describe possible interactions of leptin, adiponectin, FTO rs9939609, and TMEM18 rs6548238 in children and adolescents with asthma, under the influence of obesity." (PMID 39159917, 2025). "In studies conducted in adults, SNPs in the genes FTO, MC4R, TMEM18, TNNI3K, SEC16B, GNPDA2, and POMC are strongly associated with obesity risk." (PMID 40722558, 2025). "The detected interactions between low PA and the FTO rs1421085 or the TMEM18 rs7561317 increased all obesity-related outcomes." (PMID 39283705, 2025). "TMEM18 expression is downregulated in the adipose tissue of children with obesity, correlating with impaired adipocyte formation and insulin resistance." (PMID 41082226, 2025). "These variants mapped to well-established obesity-related genes and loci, such as POC5, MC4R, TMEM18, and the FTO locus." (PMID 38200577, 2024). "Multiple studies have hinted at the potential influence of particular genes linked to obesity risk (i.e., FTO, MC4R, and TMEM18) on GWG, emphasizing the necessity for in-depth investigations into their roles." (PMID 38613027, 2024). "For obesity, TMEM18 and TFAP2B were identified here for the first time as loci for BMI or weight change." (PMID 39609904, 2024). "Trying further to understand the pathophysiological mechanisms of TMEM18-mediated obesity, Landgraf and colleagues in 2020 turned their research towards adipose tissue metabolism instead of the central nervous system." (PMID 36986146, 2023). "Thus, indicating that the attenuation of the obesity risk and a reduction in BMI of the TMEM18 rs939583 homozygotes (TT) carriers could be achieved through engagement in PA for at least (minimum) 30 min/week with further BMI reduction when engaging in PA for >90 min/week." (PMID 36678137, 2023). "The TMEM18 is a preserved gene and has a well-established role among genes involved in obesity pathogenesis." (PMID 36986146, 2023). "In the inflammatory state of obesity, TMEM18 downregulation reduces PPARG1 levels, contributing to the metabolic dysregulation, adipocyte hypertrophy, adiponectin reduction, impaired glucose, and lipid metabolism and obesity aggravation." (PMID 36986146, 2023). "The TMEM18 obesity gene is highly conserved in different species that diverged from the human lineage." (PMID 36678137, 2023). "TMEM18 and SEC16B were associated with an increased risk of obesity of 27% and 40%, respectively, in Hispanic/Latino children (22–88% frequency)." (PMID 36499740, 2022). "Herein, we focused on four ORGs: fat mass and obesity-associated (FTO), melanocortin-4 receptor (MC4R), glucosamine-6-phosphate deaminase 2 (GNPDA2), and transmembrane protein 18 (TMEM18)." (PMID 36289871, 2022). "They analyzed the five obesity-associated genetic variants (MC4R rs17782313, BDNF rs6265, FTO rs1421085, TMEM18 rs7561317, and NEGR1 rs2815752)." (PMID 35627568, 2022). "We constructed a genetic risk score (GRS) based on five genetic variants (MC4R rs17782313, BDNF rs6265, FTO rs1421085, TMEM18 rs7561317, and NEGR1 rs2815752) and examined its association with obesity-related traits in a sample of Pakistanis." (PMID 33859285, 2021). "Several obesity susceptibility loci in genes, including GNPDA2, SH2B1, TMEM18, MTCH2, CDKAL1, FAIM2, and MC4R, have been identified by genome-wide association studies." (PMID 32228543, 2020).